AGPS (alkylglycerone phosphate synthase)
Description:
Catalyzes the exchange of the acyl chain in acyl-dihydroxyacetonephosphate (acyl-DHAP) for a long chain fatty alcohol, yielding the first ether linked intermediate, i.e. alkyl-dihydroxyacetonephosphate (alkyl-DHAP), in the pathway of ether lipid biosynthesis.
Synonyms: ADHAPS; ADAS; ALDHPSY; ADPS; ADAP-S; RCDP3
Tractability: PROTAC: ubiquitination databases record sites on it; its protein half-life has been measured.
Target class: Enzyme; Transferase
Gene: Protein-coding gene on chromosome 2 (177,392,576 to 177,567,024, forward strand). Ensembl gene ENSG00000018510.
Subcellular location: Peroxisome membrane; Peroxisome
Subcellular location (Human Protein Atlas): Peroxisomes
Pathways (Reactome):
Protein localization: Peroxisomal protein import; TYSND1 cleaves peroxisomal proteins
Metabolism: Plasmalogen biosynthesis
Gene Ontology:
Molecular function: alkylglycerone-phosphate synthase activity; protein binding; FAD binding; catalytic activity; flavin adenine dinucleotide binding
Biological process: lipid biosynthetic process; ether lipid biosynthetic process
Cellular component: membrane; mitochondrion; peroxisomal membrane; peroxisome; cytosol; peroxisomal matrix
Genetic constraint (gnomAD): Loss-of-function variants: 12 observed, 47.65 expected, observed/expected ratio (o/e) 0.25, 90% interval 0.16 to 0.41. The upper end of that interval is the gene's LOEUF score, 0.41, which puts it in group 1 of 6, group 1 being the genes least tolerant of losing a copy. Missense variants: 427 observed, 617.88 expected, observed/expected ratio (o/e) 0.69, 90% interval 0.64 to 0.75. Synonymous variants: 244 observed, 232.44 expected, observed/expected ratio (o/e) 1.05, 90% interval 0.94 to 1.17.
Gene-disease validity (ClinGen):
ClinGen rates the evidence that AGPS causes each of these diseases.
alkylglycerone-phosphate synthase deficiency (autosomal recessive): Definitive. Any disorder of plasmalogen biosynthesis in which the cause of the disease is a mutation in the AGPS gene.
Homologues: Orthologues: chimpanzee AGPS (99% identical), macaque AGPS (99% identical), rabbit AGPS (95% identical), guinea pig AGPS (93% identical), mouse Agps (90% identical), rat Agps (90% identical), dog AGPS (89% identical), pig AGPS (84% identical), tropical clawed frog agps (76% identical), zebrafish agps (71% identical), Drosophila melanogaster Agps (49% identical), Caenorhabditis elegans ads-1 (47% identical). Paralogues in human: LDHD (18% identical), D2HGDH (17% identical).
Diseases named in the same sentence as AGPS in open-access papers:
AGPS is named in the same sentence as 40 diseases in open-access papers, as found by Europe PMC text mining. Sharing a sentence is not in itself a finding about the gene and the disease. The quoted sentences say what the papers report.
rhizomelic chondrodysplasia punctata (9 papers, 2011 to 2025). Rhizomelic chondrodysplasia is a form chondrodysplasia punctata, a group of diseases in which the common characteristic is calcifications near joints at birth. "Genetic deficiency or cellular mislocalization of one of the two peroxisomal enzymes that initiate plasmalogen biosynthesis, GNPAT and AGPS, results in the severe disorder rhizomelic chondrodysplasia punctata (RCDP)." (PMID 21679470, 2011). "Furthermore, loss-of-function mutations in four genes (PEX7, GNPAT, AGPS, and FAR1) that mediate peroxisomal synthesis of AAG, a necessary substrate for synthesis of plasmenyl-PE and plasmenyl-PC, result in rhizomelic chondrodysplasia punctata (RCDP)." (PMID 38582453, 2024).
melanoma (7 papers, 2016 to 2024). A malignant, usually aggressive tumor composed of atypical, neoplastic melanocytes. "Recently, AGPS overexpression was associated with cancer cell aggressiveness and invasiveness in primary breast tumors and cancer cell lines (breast (231MFP), melanoma (C8161), and prostate (PC3) cancer cells)." (PMID 32443825, 2020). "Upon short hairpin RNA (shRNA)-mediated knockdown of AGPS in breast 231MFP and C8161 melanoma cells, the authors showed that both alkyl-LPA and its phospholipid metabolites (plasmanyl and plasmenyl species of PE and PC) were reduced in these cancer cell lines." (PMID 33430006, 2021). "First, we can conclude that our MS approach allows detection of three HLA-A2 restricted neoepitopes presented on the melanoma cells (AGPS, ENC1, CCT4)." (PMID 31921104, 2019). "After a 10-day course of treatment, melanomas were collected and analyzed by flow cytometry to confirm that the NNC+PPMP therapy decreased the abundance of CD36+ drug-tolerant cells and reduced AGPS expression." (PMID 37616051, 2023). "To summarize, increased peroxisomal/AGPS activity and UGCG occur in a significant proportion of relapsed melanomas, which are likely driven through the CD36+ drug-tolerant SMC state." (PMID 37616051, 2023).
breast carcinoma (4 papers, 2016 to 2024). "To study the expression of AGPS and SK3 in breast cancers, we analyzed AGPS and KCNN3 mRNA (coding for SK3 protein) expressions in 50 invasive breast cancer biopsies (cohort 1)." (PMID 38642894, 2024). "This is in line with a study showing that AGPS is overexpressed in breast cancer tissues compared to noncancerous tissues as well as with our data showing that the expressions of SK3 and AGPS is correlated in human breast tissues." (PMID 38642894, 2024). "However, changes in AGP levels of serum and changes in glycosylation of AGPs in breast cancer have not been specifically studied." (PMID 32627751, 2020). "One study showed that alkylglycerone phosphate synthase (AGPS), the key enzyme in natural EL synthesis, was overexpressed in breast cancer tissues compared to noncancerous tissues." (PMID 38642894, 2024).
prostate carcinoma (4 papers, 2021 to 2025). A carcinoma that arises from epithelial cells of the prostate gland. "Immunohistochemistry was undertaken to explore the protein expression of AGPS in prostate cancer tissues compared with normal tissues." (PMID 38200609, 2024). "CCK8 assay and colony formation assay were used to illustrate the key role of AGPS in the progression of prostate cancer in vitro." (PMID 38200609, 2024). "Then, we detected the protein levels of AGPS between prostate tissues and the normal tissues, result suggested that AGPS protein expression decreased in prostate cancer compared with the normal tissues." (PMID 38200609, 2024). "AGPS protein expression was downregulated in prostate cancer tissues compared with normal tissues from the first affiliated hospital of Zhengzhou University dataset." (PMID 38200609, 2024). "The xenograft model was established to verify the key role of AGPS in the progression of prostate cancer in vivo." (PMID 38200609, 2024). "In addition, AGPS can promote ferroptosis by modulating the function of peroxisome-resulting in the lower survival of prostate cancer cells." (PMID 38200609, 2024). "Additionally, we examined the protein expression of AGPS in different prostate cancer cell lines by Western blot, which lead to the same results." (PMID 38200609, 2024). "In order to investigate whether AGPS acts through the ferroptosis in prostate cancer, we conducted colony formation experiments as an initial approach." (PMID 38200609, 2024). "The AGPS degradation-induced enrichment of membrane polyunsaturated fatty acids (PUFAs) synergizes with ML210-mediated GPX4 inhibition, significantly enhancing ferroptosis in prostate cancer cells." (PMID 40427071, 2025). "Since the key function of AGPS is to synthesize EL and that the SK3 channel was previously found to be regulated by EL analogs, we then investigated whether knocking down the AGPS affected SK3 expression in various cancer cell lines (breast and prostate cancer, osteosarcoma)." (PMID 38642894, 2024).
Clear cell renal cell carcinoma (3 papers, 2025). "Another crucial enzyme in PUFA synthesis is alkylglycerone phosphate synthase (AGPS), and studies have shown that the overexpression of AGPS in renal clear cell carcinoma results in elevated levels of PUFAs in cells." (PMID 40709182, 2025). "Clear cell renal cell carcinoma establishes ferroptosis sensitivity through alkylglycerone-phosphate synthase (AGPS)-dependent PUFA-PL accumulation." (PMID 40892295, 2025). "Clear-cell renal cell carcinoma (ccRCC) cells show elevated levels of PUFA-ePLs, likely due to their increased expression of alkylglycerone phosphate synthase (AGPS, an essential enzyme in the synthesis of PUFA-ePLs), which makes them susceptible to ferroptosis." (PMID 40837737, 2025).
glioma (3 papers, 2016 to 2024). A benign or malignant brain and spinal cord tumor that arises from glial cells (astrocytes, oligodendrocytes, ependymal cells). "It has been reported that AGPS can inhibit the progression of hepatocellular carcinoma and glioma by regulating the cell cycle and the activity of signal transduction pathways such as MAPK." (PMID 38200609, 2024). "The previous research of our group also showed that silencing the expression of AGPS can inhibit the proliferation and invasion of glioma cells in vitro and inhibit the expression of ether esters." (PMID 34621897, 2021). "Silencing the expression of AGPS in glioma cells can downregulate HNRNPK, which proves the correlation between the two expressions." (PMID 34621897, 2021). "Transcriptional regulators of HNRNPK such as brain-derived neurotrophic factor (BDNF) were upregulated in gliomas, and we hypothesized that the AGPS-HNRNPK complex could facilitate to regulate tumor-related mRNA by BDNF, which would be explored in further study." (PMID 34621897, 2021). "Therefore, AGPS may be a potential target for the diagnosis and treatment of glioma." (PMID 34621897, 2021). "Through cell experiments, this study found that silencing AGPS can inhibit the in vitro proliferation of U251, H4, and TJ905 glioma cells and downregulate the tumor-related lipids MAGe, LPAe, LPCe, LPEe, PI, PC, and PS." (PMID 34621897, 2021).
hepatic carcinoma (3 papers, 2016 to 2025). "Dysregulation of peroxisomal enzymes such as AGPS and GNPAT has been shown to lead to the development of hepatocellular carcinoma." (PMID 40943222, 2025).
breast tumors (2 papers, 2020 to 2022). "Although the role of ether lipids in CRC is relatively poorly understood, ether lipids, and the rate-limiting enzyme involved in ether lipid biosynthesis, alkylglycerone phosphate synthase (AGPS), have been reported to be elevated in breast tumour tissue compared to normal tissue." (PMID 35954376, 2022).
peroxisomal disease (2 papers, 2025). A group of congenital disorders of lipid metabolism, caused by loss of the normal peroxisomes. "RCDP is a peroxisomal disorder caused by mutations in ether lipid (plasmalogen) biosynthesis-associated genes such as alkylglycerone-phosphate synthase (AGPS), glycerol-3-phosphate acyltransferase (GNPAT), and fatty acyl-CoA reductase 1 enzyme (FAR1)." (PMID 40943222, 2025). "RCDP is a recessive peroxisomal disease caused by variants in five genes: AGPS, FAR1, GNPAT, PEX5, and PEX7, which encode alkylglycerone phosphate synthase, fatty alcohol reductase 1, glycerone-phosphate O-acyltransferase, and the peroxisomal biogenesis factors 5 and 7, respectively." (PMID 40394457, 2025).
Alpha-thalassemia (1 paper, 2019). Alpha-thalassemia is an inherited hemoglobinopathy characterized by impaired synthesis of alpha-globin chains leading to a variable clinical picture depending on the number of affected alleles. "At the global level, there were two highly connected genes, AGPS (Alkylglycerone Phosphate Synthase) and ATRX (Alpha Thalassemia/Mental Retardation Syndrome, X-Linked), regulated dozens of genes directly (41 and 32 respectively)." (PMID 31569720, 2019).
cardiomyopathies (1 paper, 2024). "Mutations in AGPS, another PEX7-dependent PTS2-protein, also result in cardiomyopathies." (PMID 38365851, 2024).
cataract (1 paper, 2014). Partial or complete opacity of the crystalline lens of one or both eyes that decreases visual acuity and eventually results in blindness. "Mutations in AGPS are associated with rhizomelic chondrodysplasia punctata, type 3, a multisystem developmental disorder in which patients frequently develop cataracts." (PMID 25233373, 2014).
hyperopia (1 paper, 2014). A refractive error in which rays of light entering the eye parallel to the optic axis are brought to a focus behind the retina, as a result of the eyeball being too short from front to back. "However, the signal in our hyperopia analysis stretches across 3 genes: PDE11A; tetratricopeptide repeat domain 30A (TTC30A) protein; and alkylglycerone phosphate synthase (AGPS, MIM:603051)." (PMID 25233373, 2014).
lymphoma (1 paper, 2020). A malignant (clonal) proliferation of B- lymphocytes or T- lymphocytes which involves the lymph nodes, bone marrow and/or extranodal sites. "In addition to AGPS, elevated expression of FAR1, FAR2, and GNPAT, all of which are involved in ether phospholipid biosynthesis, was observed in aggressive lymphoma cells derived from lymphoma patients who were refractory to oxidative stress-inducing therapy." (PMID 32674458, 2020).
myocardial infarction (1 paper, 2024). Gross necrosis of the myocardium, as a result of interruption of the blood supply to the area, as in coronary thrombosis. "The involvement of genes such as AGPS, MYO9B, PYGB, TOM1, UBA52, and UBB in myocardial infarction is first reported in this study." (PMID 39872885, 2024).
Obesity (1 paper, 2020). Accumulation of substantial excess body fat. "In general, n-3 AGPs have been shown to have effects against obesity, steatosis and inflammation, as well as glucose and lipid metabolism." (PMID 33114278, 2020).
ovarian carcinoma (1 paper, 2024). A malignant neoplasm originating from the surface ovarian epithelium. "In order to further analyse the importance of the ether lipid synthesis gene, GNPAT and AGPS were compared side by side under different ovarian cancer conditions." (PMID 39700026, 2024). "In summary, the TCGA analysis of endogenous PE O– synthesis revealed that AGPS might be critical for ovarian cancer chemotherapy‐related prognosis." (PMID 39700026, 2024).
prostate tumors (1 paper, 2020). "Consistent with the microarray data, we found a higher expression of HMGCS1 (3.5-fold), HMGCR (2.5-fold), SCD1 (2.5-fold), AGPS (1.9-fold), FABP4 (2.5-fold), DPT (2.2- fold), and PTEN (1.56-fold decline) in prostate tumors of LPB-Tag genotype when compared with the prostates of other genotypes." (PMID 32180899, 2020).
rheumatoid arthritis (1 paper, 2009). A chronic, systemic autoimmune disorder characterized by inflammation in the synovial membranes and articular surfaces. "It is hypothesized that AGPs may form part of a negative feedback mechanism which is inadequate to prevent disease progression in rheumatoid arthritis." (PMID 19710928, 2009).
cancer (25 papers, 2016 to 2024). A tumor composed of atypical neoplastic, often pleomorphic cells that invade other tissues. "The pathogenic impairments conferred by AGPS knockdown in cancer cells are due to the specific depletion of the oncogenic signaling lipid lysophosphatidic acid ether and prostaglandins." (PMID 29514688, 2018). "Invasion-related genes such as the MMP were previously reported to be regulated by AGPS expression in cancer cells." (PMID 38642894, 2024). "FR1 and FR2 cells can reduce PUFAePL levels by spontaneously downregulating AGPS, thereby decreasing cancer cell sensitivity to iron-dependent cell death, promoting cancer cell proliferation, and metastasis." (PMID 39021564, 2024). "Elevation of plasmalogens has been shown in several cancer cells, which is likely associated with the pathogenicity of tumors because an inhibitor of AGPS lowers the plasmalogen levels and suppresses the pathogenicity of various types of cancer cells in vitro." (PMID 35832735, 2022). "Conversely, the overexpression of AGPS converted benign cancer cells into more aggressive subtypes with respect to cell migration and serum-free survival." (PMID 33430006, 2021). "Attempts to develop pharmacological tools to inactivate AGPS led to the use of at least two AGPS inhibitors that lowered ether lipid levels and impaired the pathogenicity of various cancer cells." (PMID 32674458, 2020). "Further, the levels of ether phospholipids in aggressive cancer cells were higher than those in less aggressive cancer cells, and the cellular amount of ether phospholipid displayed a positive correlation with AGPS expression." (PMID 32674458, 2020). "Remarkably, cancer cells with highly saturated lipids require genes involved in peroxisome ether phospholipid synthesis, such as AGPS and FAR1, for their growth." (PMID 32674458, 2020). "AGPS mRNA levels were also overexpressed in all cell lines, although values varied considerably: with a 4-fold increase in LS174t while the rest of cancer cells showed a 1.4-fold change." (PMID 32443825, 2020). "The largest impact was observed in AGPS expression, showing a 14- to 70-fold increase depending on the cancer cell line." (PMID 32443825, 2020). "Consistently, we showed that not only was AGPS overexpressed in all cancer cell lines but also between cell lines isolated from primary tumors or metastatic sites." (PMID 32443825, 2020). "Taking into account the fact that the levels of ether lipids are positively associated with the tumor metastatic capacity of a cell line, our results consolidate AGPS expression as a good biomarker to assess the metastatic capacity of a cancer cell." (PMID 32443825, 2020). "AGPS is a metabolic enzyme, a critical component in the synthesis of ether lipids, and is up-regulated across multiple types of aggressive human cancer cells and primary tumors." (PMID 31569720, 2019). "Previous studies have also shown the potential of AGPS as a therapeutic target of cancer, and multiple AGPS inhibitors are in development." (PMID 31569720, 2019). "A small molecule screen identified an inhibitor of AGPS that decreases ether lipid levels and appears to reduce pathogenicity of human cancer cells in vitro." (PMID 28523433, 2018). "Remarkably, the critical AGPS enzyme is heightened in aggressive cancer cells and primary human breast tumors, and its genetic ablation significantly impairs cancer aggressiveness and tumorigenesis." (PMID 30219925, 2018). "AGPS knockdown impaired experimental cancer pathogenesis, including cell survival, migration, and invasion." (PMID 29514688, 2018). "Multiple DEGs, including FEN1, BCAT1, AGPS and CCL3, have been implicated in the progression of various cancers." (PMID 29033691, 2017). "Therefore, regulating cancer cell sensitivity to iron-dependent cell death by modulating AGPS expression can serve as a therapeutic strategy for treating iron-death-insensitive cancer cells." (PMID 39021564, 2024).